MEG3 (maternally expressed 3)
Diseases named in the same sentence as MEG3 in open-access papers (continued):
Sharing a sentence is not in itself a finding about the gene and the disease.
psychosis (4 papers, 2018 to 2024). "The expression of MEG3 in immune cells was reported to be differentially expressed in drug naïve psychosis patients compared to those treated with risperidone." (PMID 35664469, 2022). "The expression of MEG3 is significantly reduced in participants with psychosis on antipsychotics when compared to the drug naïve participants with psychosis." (PMID 30567388, 2018). "To advance our understanding of heterochromatin function in psychosis, and the modification of expression of lncRNAs with antipsychotics, we selected three lncRNA molecules as per the criterion noted: MEG3, PINT and GAS5." (PMID 30567388, 2018). "Our results suggest that these lncRNAs (particularly, MEG3) are identified as plausible markers to study the epigenetic mechanisms involved in psychosis." (PMID 30567388, 2018). "The expression of MEG3 was found to be higher in participants with psychosis (n = 86) when compared to control participants (n = 44)." (PMID 30567388, 2018). "Specifically, our results indicate that MEG3, a lncRNA that binds to a protein domain within JARID2 of the PRC2 repressome complex, is elevated in a subgroup of participants with psychosis." (PMID 30567388, 2018).
viral myocarditis (4 papers, 2020 to 2023). Myocarditis that is caused by an infection with a viral agent. "The downregulation of the lncRNA maternally expressed 3 (MEG3) in a murine model of CVB3-induced viral myocarditis reduces M1 macrophage polarization and elevates M2 macrophage polarization via the miR-223/TRAF6/NF-κB pathway, thus relieving myocarditis." (PMID 37259293, 2023). "For example, lncRNA MEG3 inhibits M2 macrophage polarization by activating TRAF6 via miRNA-223 downregulation in viral myocarditis." (PMID 34504807, 2021). "Moreover, in the viral myocarditis (VMC) mouse model, long non-coding RNA (lncRNA) maternally expressed 3 (MEG3) expression is high and miR-223 expression is low." (PMID 34956210, 2021).
adenoma (3 papers, 2014 to 2024). A neoplasm arising from the epithelium. "It has been determined that the MEG3 gene acts as a suppressor of adenoma development and is exclusively present in normal pituitary tissue (OMIM 605636), whereas the PROP1 gene is detected in adenomas (OMIM 601538)." (PMID 39022728, 2024).
aplastic anemia (3 papers, 2022 to 2024). Anemia resulting from bone marrow failure (aplastic or hypoplastic bone marrow). "High methylation of the promoter of the LncRNA MEG3 gene in children with aplastic anemia (AA) inhibits the expression of LncRNA MEG3." (PMID 39015772, 2024). "Indeed, MEG3, a long non-coding RNA can modulate TIGIT expression on CD4+ T cells from aplastic anaemia patients." (PMID 38077329, 2023).
cerebrovascular diseases (3 papers, 2022 to 2025). "Among lncRNAs related to cardio-cerebrovascular diseases, lncR Meg3 confers a high risk of cardio-cerebrovascular diseases." (PMID 36968595, 2023). "MEG3 is another important lncRNA that has been extensively studiedand reported to be associated with many human diseases, including metabolic, immunesystem, cardiovascular, and cerebrovascular diseases." (PMID 41123190, 2025). "For another, a majority of studies of the etiology of MEG3 and cardio-cerebrovascular diseases rely on experiments in immortalized and primary cells and lack relevant in vitro data analysis." (PMID 36968595, 2023). "Is MEG3 only applicable to some specific therapeutic targets of cardio-cerebrovascular diseases?" (PMID 36968595, 2023). "Many bioactive compounds derived from natural plants have been shown to have the ability to regulate lncRNA expression via molecular mechanisms, and MEG3 research may offer new strategies for finding pharmacotherapy in the treatment of cardio-cerebrovascular diseases." (PMID 36968595, 2023).
cholestasis (3 papers, 2020 to 2023). Impairment of the bile flow caused by obstruction within the liver, or outside the liver in the bile duct system. "Maternally expressed 3 (MEG3) serves as a guide RNA scaffold by recruit polypyrimidine tract binding protein 1 (PTBP1) to destabilize Shp mRNA to cause cholestasis." (PMID 32670859, 2020). "MEG3 maintains systemic glucose homeostasis independently of its effects on systemic inflammation, and it can also drive fibrosis and even cirrhosis via the promotion of bile acid synthesis and cholestasis." (PMID 36979495, 2023).
Cirrhosis (3 papers, 2016 to 2023). A chronic disorder of the liver in which liver tissue becomes scarred and is partially replaced by regenerative nodules and fibrotic tissue resulting in loss of liver function. "Univariate analysis identified the following 11 lncRNAs as significantly correlated with RFS of patients with cirrhosis: SH3RF3-AS1, AC104117.3, AC136475.3, LINC00239, MRPL23-AS1, LINC00494, LINC01970, MEG3, Z93930.3, MIR9-3HG and TRBV11-2." (PMID 32592379, 2020). "In contrast to HOTTIP, H19 and MEG3, we found that ANRIL expression was up-regulated both in cirrhosis vs. normal liver and in HCC vs. cirrhosis, suggesting its involvement in the process of hepatocarcinogenesis from normal liver through the precancerous stage of cirrhosis." (PMID 27894309, 2016).
endometriosis (3 papers, 2021 to 2023). The growth of functional endometrial tissue in anatomic sites outside the uterine body. "Recent studies have found that lncRNA-MEG3(MEG3) plays an important role in the development of EMs (Endometriosis), but the specific mechanism needs to be further explored." (PMID 37392565, 2023). "Third, studies showed that lncRNA maternally expressed 3 (MEG3-210) has a regulatory mechanism in endometriosis." (PMID 34638965, 2021). "In an example of direct regulation of a signaling pathway in endometriosis, the lncRNA MEG3-210 has been shown to regulate endometriosis stromal cell migration, invasion, and apoptosis through the p38 MAPK and PKA/SERCA2 signaling pathways." (PMID 34768856, 2021). "Although MEG3 has been widely and deeply studied in tumors, the role and related mechanisms of MEG3 in endometriosis remain unclear." (PMID 37392565, 2023).
Epidermoid Carcinoma (3 papers, 2013 to 2023). "We next performed qRT-PCR analysis to examine the expression of MEG3 in 7 human NSCLC cell lines, including both adenocarcinoma and squamous carcinoma subtypes." (PMID 24098911, 2013).
hepatoblastoma (3 papers, 2014 to 2026). Hepatoblastoma (HB) is a malignant hepatic tumor and is the most common pediatric liver cancer. "This study investigates the expression and functional significance of the lncRNA, maternally expressed gene 3 (MEG3), in a metastatic hepatoblastoma model." (PMID 41744804, 2026). "RNA sequencing comparing the metastatic hepatoblastoma cell line, HLM_2, with its parental HuH6 cell line identified MEG3 as being significantly upregulated in metastatic cells." (PMID 41744804, 2026). "MEG3 expression was examined using hepatoblastoma patient datasets and validated using qPCR in cell lines, orthotopic tumors, and COA67 patient-derived xenografts." (PMID 41744804, 2026). "MEG3 upregulation has also been observed in hepatoblastoma tissues compared to paired distant healthy tissues, suggesting that MEG3 pro-apoptotic function could be counteracted in some tumors." (PMID 29560114, 2018).
infertile (3 papers, 2016 to 2025). "Aberrant methylation of H19, Potassium Voltage-Gated Channel Subfamily Q Member 1 Opposite Strand/Antisense Transcript 1 (KCNQ1OT1), and Maternally Expressed 3 (MEG3) has been described in infertile men’s sperm and in embryos from ICSI cycles." (PMID 41465244, 2025). "GTL2/MEG3 was found differentially expressed between infertile males and fertile controls, and the methylation differences showed significant effect." (PMID 26938548, 2016).
nicotine dependence (3 papers, 2014 to 2017). Physical and psychological dependence on nicotine. "Of particular interest were findings in FRMD4A, ATP9A, GALNT2, and MEG3—genes that are implicated in processes related to nicotine dependence, smoking cessation, and placental and embryonic development." (PMID 24906187, 2014).
pancreatic ductal adenocarcinoma (3 papers, 2020 to 2022). An infiltrating adenocarcinoma that arises from the epithelial cells of the pancreas. "Pan and colleagues demonstrated using scRNA-seq of pancreatic ductal carcinomas that MEG3 expression was significantly enriched in CAFs of primary tumors, and MEG3 expression was significantly associated with epithelial-mesenchymal transition signatures." (PMID 36231143, 2022).
renal carcinoma (3 papers, 2021 to 2026). A carcinoma arising from the epithelium of the renal parenchyma or the renal pelvis. "Several lncRNAs (GAS5, MEG3/GTL2, HIF-1α-AS1, H19, KCQN1OT1, MALAT1 and HOTAIR) have been implicated in renal cancer." (PMID 39575481, 2025). "Among all the lncRNA candidates predicted by the BiGAN as being associated with renal cancer, 7 lncRNAs were among the top 10 in the predicted list, (MALAT1 1st, HOTAIR 2nd, PVT1 3rd, NBAT1 4th, UCA1 5th, H19 6th, and MEG3 7th)." (PMID 34193046, 2021).
Silver-Russell syndrome (3 papers, 2019 to 2024). Silver-Russell syndrome is characterized by growth retardation with antenatal onset, characteristic facies and limb asymmetry. "Similarly as for the H19 DMR—where epigenetic alterations that affect CTCF binding cause the growth-related imprinting disorders Beckwith-Wiedemann Syndrome (BWS) and Silver-Russell Syndrome (SRS) —maternal CTCF binding at the Meg3 DMR is evolutionarily conserved in humans." (PMID 31831055, 2019).
somatotroph adenomas (3 papers, 2020 to 2024). "Similar results were obtained with MEG3, which has already been reported to be one of the most significantly upregulated differentially expressed genes in somatotroph adenomas compared with other PitNET subtypes." (PMID 39596626, 2024). "We observed that MEG3/8/9 and miR-377 in the 14q32.2 region showed a widespread increase in somatotroph adenomas." (PMID 33472171, 2020). "Combined with the clinical phenotype, DLK1 and MEG3 were identified as characteristic molecules in somatotroph adenomas." (PMID 33472171, 2020). "Here, we showed the critical role of the DLK1/MEG3 locus in the differentiation of PitNETs in patients depending on the level of PIT1 and suggested the DLK1/MEG3 locus as a potential therapeutic target for somatotroph adenoma patients." (PMID 33472171, 2020). "Hypermethylation of IG-DMR at the DLK1/MEG3 locus is the reason for the loss of MEG3 that occurs only in gonadotroph adenomas, and no gene in the DLK1/MEG3 locus was significantly downregulated in somatotroph adenomas compared to other PitNETs." (PMID 33472171, 2020). "Our observations that MEG3 activation in somatotroph cells due to an activating GNAS mutation, concomitantly the inactivation of Wnt/β-catenin pathway and inhibition of EMT may explain distinctive somatotroph adenoma features." (PMID 38827318, 2024). "The imprinting disorders of the 14q32.2 region in somatotroph adenomas compared with other subtypes were identified, and a high-resolution profile at 14q32.2 (chr14:100,487,787-101,563,452, including DLK1/MEG3 locus) is shown." (PMID 33472171, 2020). "AC126177.8, AC355974.2, LINC02475, MEG3, MEG9 and MiR7-3HG were the most significantly different lncRNAs in somatotroph adenomas." (PMID 33472171, 2020). "At least, combining analogs of somatostatin and blockade of the DLK1/MEG3 locus could be an effective treatment strategy for somatotroph adenomas, especially for patients with overactivation of the DLK1/MEG3 locus and resistance to standard treatment." (PMID 33472171, 2020).
steatosis (3 papers, 2018 to 2023). Increased lipid within the cytoplasm of cells. "Taken together, these data suggest that knocking down SIRT6 is sufficient to aggravate FFA-induced steatosis and to dampen the protection conferred by overexpressing MEG3." (PMID 35256601, 2022). "MEG3 expression was significantly lower in primary hepatocytes from NASH than in those from simple steatosis." (PMID 35256601, 2022). "In contrary to MEG3, miR-let-7c-5p overexpression attenuated EtOH-induced steatosis and apoptosis, as well as suppressed EtOH-induced increase in NLRC5 expression." (PMID 29692724, 2018). "Knockdown of MEG3 contributed to attenuation of EtOH-induced steatosis and apoptosis in AML-12 cells." (PMID 29692724, 2018). "MEG3 reduction may also lead to liver inflammation and steatosis through the miR-34a/Nrf2 and miR-34a/SIRT1 signaling axes." (PMID 36742142, 2023). "More importantly, we compared MEG3 expression in primary hepatocytes from healthy individuals and patients suffering from earlier steatosis or later-stage fibrosis and revealed the reverse correlation between MEG3 level and the severity of NAFLD, evidencing the clinical relevance of MEG3 in NAFLD." (PMID 35256601, 2022). "It suggested that MEG3 may play a vital role in ethanol-induced hepatocyte steatosis and apoptosis." (PMID 29692724, 2018).
subarachnoid hemorrhage (3 papers, 2020 to 2022). A serious neurological disorder characterized by intracranial hemorrhage into the subarachnoid space. "MEG3 expression is increased in patients with subarachnoid haemorrhage relative to that in healthy controls and participates in the SAH‐induced neuronal cell injury." (PMID 32436312, 2020). "LncRNA MEG3 expression was significantly increased in the temporal cortex of rats with subarachnoid hemorrhage and in the cerebrospinal fluid of patients with subarachnoid hemorrhage, while the expression of the PI3K/Akt signaling pathway was decreased, which promoted neuronal apoptosis." (PMID 36523500, 2022).
testicular germ cell tumor (3 papers, 2018 to 2022). A germ cell tumor arising from the testis. "Crosstalk between MEG3 and miR-1297 regulates the growth of testicular germ cell tumor through PTEN/PI3K/AKT pathway." (PMID 29449541, 2018).
acute kidney injury (2 papers, 2021 to 2024). Sudden and sustained deterioration of the kidney function characterized by decreased glomerular filtration rate, increased serum creatinine or oliguria. "The gene MEG3 is known to be a significant mediator of ischemia–reperfusion injury (IRI)-induced acute kidney injury (AKI), where it is upregulated in the renal cortex in IRI mice and exacerbates IR-induced AKI." (PMID 38347632, 2024).
anal abscess (2 papers, 2022 to 2024). "Notably, MEG3 expression levels are significantly elevated in the peripheral blood of CD patients compared to healthy individuals, indicating its potential involvement in exacerbating the inflammatory response associated with anal abscess, a common complication of CD." (PMID 38961978, 2024). "This work aimed to study the correlation between SNPs in MEG3/miR-181b and the severity of anal abscess in patients with Crohn’s disease." (PMID 35422450, 2022). "In conclusion, our study demonstrated that the two SNPs, rs322931 (C>T) in miR-181b and rs7158663 (G>A) in MEG3, could aggravate the inflammatory response of anal abscess in patients with Crohn’s disease, via modulating the MEG3/miR-181b/TNF signaling pathway." (PMID 35422450, 2022). "Therefore, we hypothesized that the combination of SNP rs322931 (C>T) in miR-181b and rs7158663 (G>A) in MEG3 would also regulate the inflammatory response of anal abscess in patients with Crohn’s disease." (PMID 35422450, 2022).
bone cancer (2 papers, 2023 to 2024). A primary or metastatic malignant neoplasm affecting the bone or articular cartilage. "In a study on the treatment of bone tumors, MEG3 coated with modified exosomes can be efficiently diverted to tumor cells in vivo and in vitro for the treatment of bone tumors." (PMID 38107573, 2023).
chordoma (2 papers, 2017 to 2022). Chordomas are rare malignant tumors arising from embryonic remnants of the notochord in axial skeleton. "A recent study demonstrated that increased MEG3 expression inhibited the proliferation of chordoma cells, revealing the role of the imprinted gene cluster DLK1-MEG3 in the occurrence and development of chordoma." (PMID 36544907, 2022). "As determined by qPCR, MEG3 expression increased significantly in chordoma cells after transfection with the pcDNA-MEG3." (PMID 29348851, 2017). "Our lncRNA-coding gene profile revealed concomitant down-regulation of DLK1 and MEG3 in chordoma samples." (PMID 29348851, 2017). "Overexpression of MEG3 suppressed the proliferation of chordoma cells." (PMID 29348851, 2017). "The results suggest that MEG3 can effectively suppress chordoma cells proliferation." (PMID 29348851, 2017). "Our lncRNA-coding genes profile data showed that the most differentially expressed protein coding gene in chordoma was DLK1, and Cis-regulation analysis revealed that this gene was targeted by a bunch of lncRNAs, most of which were identified to be different transcripts of MEG3 and MEG8." (PMID 29348851, 2017).
chronic obstructive pulmonary disease (2 papers, 2021). A chronic and progressive lung disorder characterized by the loss of elasticity of the bronchial tree and the air sacs, destruction of the air sacs wall, thickening of the bronchial wall, and mucous accumulation in the bronchial tree. "In a study about chronic obstructive pulmonary disease, MEG3 is at a high level in lung tissues of patients, which is coincident with our findings." (PMID 34558385, 2021). "Multiple studies have shown that MEG3 is involved in regulating inflammatory-response mechanisms in various diseases such as acute pancreatitis, chronic obstructive pulmonary disease, and ultraviolet skin injury." (PMID 34012408, 2021).
dermatitis (2 papers, 2017 to 2023). An inflammatory process affecting the skin. "Additionally, the predictions for L1000 small molecules and CRISPR-KO genes that may up- or down-regulate MEG3 expression provided a possible mechanism for how MEG3 could be involved in chronic inflammation and dermatitis." (PMID 36869839, 2023). "MEG3 is co-expressed with anti-inflammatory genes that are downregulated by IL17C and IL17RB, and it is negatively correlated with genes that when knocked out in mice, it induces chronic inflammation and dermatitis." (PMID 36869839, 2023).
Duchenne muscular dystrophy (2 papers, 2016 to 2025). Duchenne muscular dystrophy (DMD) is a neuromuscular disease characterized by rapidly progressive muscle weakness and wasting due to degeneration of skeletal, smooth and cardiac muscle. "This study demonstrates that lncRNA maternally expressed gene 3 (MEG3) is preferentially expressed in slow‐twitch muscle fibers and dynamically regulated during muscle development, aging, and in the context of Duchenne muscular dystrophy (DMD)." (PMID 40285575, 2025).
dwarfism (2 papers, 2006 to 2009). "A second imprinting effect was revealed by a gene trap-LacZ insertion upstream of Meg3/Gtl2 that causes dwarfism in mice inheriting the Gtl2LacZ mutant allele from their father." (PMID 19194500, 2009).